HPS1 (HPS1 biogenesis of lysosomal organelles complex 3 subunit 1)
Description:
Component of the BLOC-3 complex, a complex that acts as a guanine exchange factor (GEF) for RAB32 and RAB38, promotes the exchange of GDP to GTP, converting them from an inactive GDP-bound form into an active GTP-bound form. The BLOC-3 complex plays an important role in the control of melanin production and melanosome biogenesis and promotes the membrane localization of RAB32 and RAB38.
Synonyms: HPS; BLOC3S1
Tractability: PROTAC: ubiquitination databases record sites on it; its protein half-life has been measured.
Gene: Protein-coding gene on chromosome 10 (98,410,939 to 98,446,966, reverse strand). Ensembl gene ENSG00000107521.
Pathways (Reactome):
Vesicle-mediated transport: RAB GEFs exchange GTP for GDP on RABs
Gene Ontology:
Molecular function: guanyl-nucleotide exchange factor activity; protein binding; protein dimerization activity
Biological process: melanosome assembly; lysosome organization; platelet dense granule organization; vesicle-mediated transport
Cellular component: BLOC-3 complex; cytoplasm; cytoplasmic vesicle; cytosol; lysosome
Genetic constraint (gnomAD): Loss-of-function variants: 53 observed, 75.79 expected, observed/expected ratio (o/e) 0.7, 90% interval 0.56 to 0.88. The upper end of that interval is the gene's LOEUF score, 0.88, which puts it in group 3 of 6, group 1 being the genes least tolerant of losing a copy. Missense variants: 803 observed, 841.53 expected, observed/expected ratio (o/e) 0.95, 90% interval 0.9 to 1.01. Synonymous variants: 365 observed, 366.76 expected, observed/expected ratio (o/e) 1, 90% interval 0.91 to 1.09.
Gene-disease validity (ClinGen):
ClinGen rates the evidence that HPS1 causes each of these diseases.
Hermansky-Pudlak syndrome 1 (autosomal recessive): Definitive.
Homologues: Orthologues: chimpanzee HPS1 (99% identical), macaque HPS1 (97% identical), rabbit HPS1 (86% identical), dog HPS1 (85% identical), rat Hps1 (82% identical), guinea pig HPS1 (81% identical), mouse Hps1 (81% identical), pig HPS1 (80% identical), tropical clawed frog hps1 (58% identical), zebrafish hps1 (53% identical), Drosophila melanogaster HPS1 (23% identical).
Diseases named in the same sentence as HPS1 in open-access papers:
HPS1 is named in the same sentence as 33 diseases in open-access papers, as found by Europe PMC text mining. Sharing a sentence is not in itself a finding about the gene and the disease. The quoted sentences say what the papers report.
pulmonary fibrosis (19 papers, 2014 to 2025). Chronic progressive interstitial lung disorder characterized by the replacement of the lung tissue by connective tissue, leading to progressive dyspnea, respiratory failure, or right heart failure. "This region has a high concentration of HPS-1 cases, and patients often present with a range of skin pigmentation and an increased risk of pulmonary fibrosis." (PMID 40698202, 2025). "generated LBOs from iPSCs and introduced HPS1 mutation to trigger an early‐onset form of pulmonary fibrosis with the accumulation of extracellular matrix and mesenchymal cells." (PMID 40387003, 2025). "The HPS1 deficiency-induced pulmonary fibrosis phenotype can be mediated by the TGF-β -IL-11 axis, and iNOS also plays a pivotal role in regulating the expression and secretion of IL-11 in activated lung fibroblasts." (PMID 39457053, 2024). "Respiratory impedance (Zrs) measured by the FOT is a valuable tool for detecting and monitoring the progression of pulmonary fibrosis in patients with HPS with the HPS-1 (c.1472_1487dup p.His497Glnfs*90) founder mutation." (PMID 39584851, 2024). "HPS progressive pulmonary fibrosis is primarily associated with dysfunction of the subunits HPS1 and HPS4 in BLOC-3 and the subunit HPS2 in the AP-3 complex." (PMID 39457053, 2024). "Lung fibrosis is the leading cause of death among adults with HPS-1 and HPS-4 genetic types, which are associated with defects in the biogenesis of lysosome-related organelles complex-3 (BLOC-3), a guanine exchange factor (GEF) for a small GTPase, Rab32." (PMID 35739508, 2022). "Hermansky–Pudlak syndrome 1 (HPS1) mutation partly accounts for the formation of intractable pulmonary fibrosis." (PMID 30534474, 2018). "Introduction of HPS1 mutation to LBOs formed lung organoids with lung fibrosis, in which extracellular matrix and mesenchymal cells accumulated." (PMID 30534474, 2018). "These are similar to the pulmonary fibrosis phenotype of HPS1, suggesting that mice or humans with BLOC-1/2 mutations may be at risk of pulmonary fibrosis." (PMID 39457053, 2024). "HPS-1 and HPS-4 are linked to pulmonary fibrosis, while HPS-2 is associated with neutropenia and infections." (PMID 40698202, 2025). "The peripheral blood environment of patients with HPS1 pulmonary fibrosis is characterized by activation and population expansion of T and B cells." (PMID 39457053, 2024). "Pulmonary fibrosis has been appreciated predominantly in HPS-1 and HPS-4 patients, whose genetic defects are in the biogenesis of lysosome-related organelle complex 3 (BLOC-3)." (PMID 39405112, 2024). "The goals of the current research are to determine the effect of CHI3L1-CRTH2 interaction on ILC2s and the contribution of ILC2 activation in pulmonary fibrosis in the Hps1−/− mouse model." (PMID 39405112, 2024). "Consistently, α1 procollagen and fibronectin expression, and the development of lung fibrosis were significantly decreased in Hps1−/−Rorafl/flIL-7Rcre mice compared with Hps1−/− mice." (PMID 39405112, 2024). "HPS-1, HPS-4, and, to a lesser extent, HPS-2 patients are at risk for pulmonary fibrosis, which is the predominant cause of mortality among this population." (PMID 35739508, 2022). "HPS-1 is characterized by the development of a highly prevalent pulmonary fibrosis in affected adults, and thus is a model for studying pulmonary fibrosis." (PMID 35509004, 2022). "The combined lysosomal and ER stress in AT2 epithelial cells results in significant AT2 epithelial cell apoptosis, airspace enlargement, fibroblast proliferation, and spontaneous lung fibrosis in HPS1/2 double mutant mice." (PMID 33841163, 2021). "Compound heterozygous mutations in HPS1 in the proband lead to disruption of HPS1 gene and clinical manifestation of HPS with severe pulmonary fibrosis." (PMID 31619213, 2019). "Patients with HPS-1 exhibit oculocutaneous albinism, colitis, bleeding and pulmonary fibrosis postulated to result from a dysregulated immune response." (PMID 27459687, 2016).
pulmonary fibrosis (continued). "Lung tissue sections from patients with advanced HPS-1 pulmonary fibrosis and IPF show numerous tryptase positive HuMCs." (PMID 27459687, 2016). "Pulmonary fibrosis has been found in three genetic variants of HPS, including HPS1, HPS2, and HPS4." (PMID 39457053, 2024). "In conclusion, these immune cell changes may lead to overactivation of the immune system in HPS1 patients, thereby exacerbating the progression of pulmonary fibrosis." (PMID 39457053, 2024). "In HPS1 pulmonary fibrosis, lung mast cells are localized in fibrotic areas of the lung parenchyma, and HPS1 dermal mast cells exhibit abnormal granulation, cellular activation, cytokine release, and synthesis of matrix components compared to the healthy controls." (PMID 39457053, 2024). "Pulmonary fibrosis is highly prevalent in patients with HPS-1 regardless of their HPS1 genetic variants." (PMID 34211981, 2021). "Importantly, in patients harboring HPS1 and HPS4 mutations, pulmonary fibrosis is highly penetrant and a leading cause of premature death in adulthood, typically around the fourth or fifth decades of life, secondary to respiratory failure." (PMID 33808351, 2021). "Individuals with a BLOC-1 and BLOC-2 related mutations present with milder OCA symptoms, and little to no pulmonary fibrosis when compared to individuals with mutations in HPS1 and HPS4 (BLOC-3 related)." (PMID 33841163, 2021). "The near-normalization of constitutive cytokine and matrix release following rescue by HPS1 transduction of HPM cells suggests that HPS-1 HuMCs may contribute to pulmonary fibrosis and constitute a target for therapeutic intervention." (PMID 27459687, 2016). "Patients with HPS1 characteristically develop severe pulmonary fibrosis." (PMID 24707413, 2014). "In addition, elevating the expression or activity of SLC7A11 may enhance the antioxidant capacity of the cells, thereby reducing HPS1 pulmonary fibrosis." (PMID 39457053, 2024). "Therefore, restoration of HSPs expression may be effective in improving epithelial cell health, thereby alleviating HPS1 pulmonary fibrosis." (PMID 39457053, 2024). "More research is needed to better define a role for HPS1 and confirm our hypothesis that progenitor mast cells in these and similar patients may be involved in pulmonary fibrosis and contribute to patient morbidity, with the possibility of suggesting new approaches to therapy." (PMID 27459687, 2016). "HPS1 and HPS4 subjects are more prone to develop pulmonary fibrosis during middle age, while HPS2 pulmonary fibrosis is more prevalent in children and young adults." (PMID 40387003, 2025). "Studies have shown that HPS1 or HPS4 lung fibers are more prone to developing pulmonary fibrosis during middle age, between the ages of 30 and 50, while HPS2 pulmonary fibrosis is more prevalent in children and young adults." (PMID 39457053, 2024). "Furthermore, the development of pulmonary fibrosis in these mice varied significantly among experiments, both in severity and localization of lesions; in several regions, large areas of inflammation occur and show the acute nature of inflammatory response in the Hps1 model." (PMID 35509004, 2022). "HPS-1 is a genetic type of Hermansky-Pudlak syndrome (HPS) with highly penetrant pulmonary fibrosis (HPSPF), a restrictive lung disease that is similar to idiopathic pulmonary fibrosis (IPF)." (PMID 35509004, 2022). "HPS-1 and idiopathic pulmonary fibrosis (IPF) alveolar interstitium showed numerous HuMCs; HPS-1 dermal mast cells exhibited abnormal granules when compared to healthy controls." (PMID 27459687, 2016). "Case A: A patient negative for pulmonary fibrosis on HRCT, homozygous for the HPS-1 mutation, had an FEV1 of 70% of the predicted value." (PMID 39584851, 2024). "It has been found that the single mutant Hps1 or Hps2 mice demonstrated increased fibrosis sensitivity but generally did not have spontaneous pulmonary fibrosis, whereas double mutant Hps1/2 mice exhibited spontaneous fibrosis with age." (PMID 39457053, 2024).
pulmonary fibrosis (continued). "In contrast, when Hps1−/− mice were bred with Rag1−/− mice to deplete T cells, Hps1−/−Rag1−/− double-mutant mice were not protected from bleomycin-induced lung fibrosis development, suggesting Th2s did not contribute to fibrosis development in this model." (PMID 39405112, 2024). "Pulmonary Fibrosis has been appreciated in HPS-1 and HPS-4 patients, whose genetic defects are in biogenesis of lysosome-related organelle complex 3 (BLOC-3), which includes HPS1 and HPS4 proteins, and, less commonly, HPS-2 patients." (PMID 35370755, 2022). "Moreover, we recognize that HPS-2 is not the major subtype to cause pulmonary fibrosis in HPS patients, and that performing similar studies with HPS-1 and HPS-4 cells would have made our work more broadly applicable." (PMID 33557836, 2021). "Furthermore, whether HPS1 patient-specific AOs can recapitulate fibroblast activation induced by epithelial cell dysfunction, which is considered as an important step in the pathogenesis of pulmonary fibrosis, has not yet been demonstrated." (PMID 34736469, 2021).
albinism (10 papers, 2018 to 2025). A congenital disorder characterized by partial or complete absence of melanin pigment in the eyes, hair, or skin. "Sequencing of the 21 known albinism genes using our next generation sequencing panel identified a heterozygous variant in the HPS1 gene, NM_000195.5:c.1718C>G, p.Pro573Arg." (PMID 39809949, 2025). "We identified one patient (family 26677) with homozygous HPS1 variants but at four years of age, only displayed oculocutaneous features of albinism." (PMID 33808351, 2021). "HPS and CHS are syndromic albinism caused by mutations in genes such as HPS1–10 and CHS1, respectively, which encode proteins HPS1, adaptor protein (AP-3) β3A, HPS3, HPS4, HPS5, HPS6, Dysbindin, BLOS3, Pallidin, AP-3 δ, and LYST." (PMID 30104399, 2018). "Among the 10 human HPS subtypes and the corresponding mouse subtypes with similar albinism phenotypes, it has been reported that hps1 gene mutations are most often responsible for HPS in humans, with deficiency of the mouse ortholog causing a similar phenotype." (PMID 35944207, 2022). "Novel and reported TYR, OCA2 and HPS-1 variants identified in albinism families in this study." (PMID 35328057, 2022). "A multicentre study of 907 patients with FH found that 67% of individuals had albinism caused by variants in GPR143, OCA2, TYR and HPS1 genes, followed by 21.8% with PAX6, 6.8% with SLC38A8 and 3.5% with FRMD7 variants." (PMID 37762234, 2023). "In order to functionally confirm that hps1 was the gene responsible for albinism in medaka, genome editing was carried out using the CRISPR/Cas9 system targeting exon 4 of hps1." (PMID 35944207, 2022). "HPS-1-affected individuals are presented with more severe ocular findings than in other subtypes, and cutaneous albinism is more prominent with increased hypopigmentation of hair and skin." (PMID 35328057, 2022). "First of all, this study demonstrates that the sequencing of whole genes, as we did here with our current diagnostic panel that contains the entirety of five major albinism genes (TYR, OCA2, SLC45A2, GPR143 and HPS1), is instrumental in identifying deep intronic splice variants in these genes." (PMID 39201349, 2024). "In the present study, we analyzed 122 heterozygous patients with albinism either by whole genome sequencing or by the use of our next-generation sequencing panel that includes the entire sequence of the TYR, OCA2, SLC45A2, GPR143 and HPS1 genes (exons, introns, flanking sequences)." (PMID 39201349, 2024).
Hermansky-Pudlak syndrome (7 papers, 2014 to 2022). Hermansky-Pudlak syndrome (HSP) is a multi-system disorder characterized by oculocutaneous albinism, bleeding diathesis and, in some cases, neutropenia, pulmonary fibrosis, or granulomatous colitis. "Taken together, these results highlight the contribution of mutations in and overall downregulation of HPS1 to an increased susceptibility to proteinuric kidney disease within the context of Hermansky-Pudlak Syndrome." (PMID 31776394, 2019). "A top-scoring event was the choice between alternate upstream and downstream 5′ss (u5′ss and d5′ss) in the Hps1 gene mutated in patients with type 1 Hermansky-Pudlak Syndrome (HPS)." (PMID 25375251, 2014). "Hps1 is essential for proper biogenesis of lysosome-related organelles and loss of its function leads to a disease called type 1 Hermansky-Pudlak Syndrome (HPS)." (PMID 25375251, 2014).
lung disease (4 papers, 2016 to 2024). "Patients with HPS-1 have also been shown to have elevated levels of MCP-1 in bronchoalveolar lavage fluid that correlate with lung disease severity." (PMID 39699958, 2024). "HPS genotypes relating to BLOC-3 components and AP-3β3A, i.e., HPS1, HPS2, and HPS4, are susceptible to the lung disease." (PMID 30060521, 2018). "Previously published accounts suggest pulmonary mast cells in patients with fibrotic lung disorders undergo a chronic process of degranulation resulting in altered granule morphology which might relate to the altered granule morphology observed in HPS-1 mast cells." (PMID 27459687, 2016). "Although this patient did not have clinical evidence of lung disease, analysis of his bronchoalveolar lavage cells identified foamy alveolar macrophages, which resemble those observed in patients with HPS-1 and may indicate a response to a pro-fibrotic alveolar milieu." (PMID 28296950, 2017).
colitis (2 papers, 2016 to 2022). Inflammation of the colon. "A reproducible murine Hps1 colitis model could facilitate these investigations and the validation of novel therapies for HPS-IBD, including rapamycin." (PMID 36302964, 2022).
granulomatous colitis (2 papers, 2022 to 2025). "For instance, HPS‐3, HPS‐5, and HPS‐6 have milder symptoms with respect to other HPS subtypes; they do not develop the pulmonary fibrosis and granulomatous colitis that are seen in patients with defective BLOC‐3 (HPS1 and HPS4), or the neutropenia that is present in defective AP‐3 (HPS2 and HPS10)." (PMID 40387003, 2025).
inflammatory bowel disease (2 papers, 2019 to 2020). A spectrum of small and large bowel inflammatory diseases of unknown etiology. "For some HPS subtypes, such as HPS-1, it is common to have symptoms of HPS-associated inflammatory bowel disease (IBD)." (PMID 33224134, 2020). "Loss of HPS1 impairs lysozyme secretion and alters the composition of intestinal microbiota, which may explain the susceptibility of HPS-associated inflammatory bowel disease." (PMID 33224134, 2020). "In addition, some patients with HPS, specifically HPS-1, − 4, and − 6, develop Crohn’s-like inflammatory bowel disease (IBD)." (PMID 30634918, 2019).
atherosclerosis (1 paper, 2019). A disease characterized by the build-up of fatty material and calcium deposition in the arterial wall resulting in partial or complete occlusion of the arterial lumen. "For example, HPS1 patients should pay more attention to diet in an effort to avoid the risk of atherosclerosis caused by a high-fat diet." (PMID 30710063, 2019).
bleeding disorders (1 paper, 2015). "A handful of the candidate defects were present in genes that had previously been associated with platelet bleeding disorders, including P2RY12, VPS33B, GATA1, ANKRD26, HPS1, VWF, and LYST22." (PMID 25556537, 2015).
chronic lung disease (1 paper, 2025). According to the definitions of the American and British Thoracic Societies, including pulmonary functional tests, X-rays, and CT scans for items such as fibrosis, bronchiectasis, bullae, emphysema, nodular or lymphomatous abnormalities. "The distinct profile of neutrophil activation markers in HPS-1 aligns with existing literature on the fibrogenic role of NETs in chronic lung diseases, such as IPF." (PMID 40355888, 2025).
emphysema (1 paper, 2017). "Experimentally engineered double mutant mice (pale ear/pearl, i.e., Hps1/Hps2) are used as mouse models of HPS lung pathology and exhibit lung inflammation and emphysema with prominent overloading of phospholipids in remarkably enlarged lamellar bodies." (PMID 28438206, 2017).
influenza (1 paper, 2024). An acute viral infection of the respiratory tract, occurring in isolated cases, in epidemics, or in pandemics; it is caused by serologically different strains of viruses (influenzaviruses) designated A, B, and C, has a 3-day incubation period, and usually lasts for 3 to 10 days. "Given the heterogeneous nature of influenza injury and previously observed AT2 cell loss in naive HPS mice, we quantified the difference in the percentages of EdU+proSP-C+ cells in WT, HPS1, and HPS2 mice." (PMID 39699958, 2024). "To examine epithelial regeneration after injury, we examined proliferating AT2 (5-ethynyl-2′-deoxyuridine–positive [EdU+], proSP-C+) cells in HPS1 and HPS2 as compared with WT mice after acute influenza infection." (PMID 39699958, 2024). "Weight change and oxygen saturation decreased similarly in WT, HPS1, and HPS2 mice during the first 10 days postinfection (dpi) with H1N1 PR8 influenza; subsequently, oxygen saturations trended lower in HPS1 and HPS2 mice, though no mortality was observed in any group." (PMID 39699958, 2024).
lysosomal storage disorders (1 paper, 2022). "We found that cholesterol, which accumulates in multiple lysosomal storage disorders, leads to reduced bacterial clearance in both control and HPS1 knockout cells." (PMID 36302964, 2022).